NEK2 (NIMA related kinase 2)
Diseases named in the same sentence as NEK2 in open-access papers (continued):
Sharing a sentence is not in itself a finding about the gene and the disease.
multiple myeloma (continued). "The expression of NEK2 and aerobic glycolysis genes was examined in plasma cells derived from 22 healthy subjects, 44 monoclonal gammopathy of undetermined significance (MGUS) patients, 305 low- and 46 high-risk myeloma patients using gene expression profiling (GEP)." (PMID 28086949, 2017). "NIMA Related Kinase 2 (NEK2) promotes aerobic glycolysis through regulating splicing of Pyruvate Kinase M1/2 (PKM) and increasing the PKM2/PKM1 ratio in myeloma cells which contributes to its oncogenic activity." (PMID 31857793, 2019). "In ALDHbr multiple myeloma cells, ALDH1A1 activates RXRα, which upregulates NIMA-related kinase 2 (NEK2), thereby activating the drug efflux pump and inducing resistance against bortezomib and doxorubicin." (PMID 30733805, 2019). "Our studies demonstrate that NEK2 promotes aerobic glycolysis through regulating splicing of PKM and increasing the PKM2/PKM1 ratio in myeloma cells which contributes to its oncogenic activity." (PMID 28086949, 2017). "NIMA-related kinase 2 (NEK2), a novel CIN gene of great interest for myeloma research, was first reported by the Schultz Lab." (PMID 29100463, 2017). "Myeloma patients with high PKM2 expression had shortened EFS (p = 0.040) and OS (p = 0.007), which is similar to NEK2 (EFS p = 0.001; OS p = 0.002)." (PMID 28086949, 2017). "NEK2 expression and PKM2 expression showed a decrease after addition of doxycycline by Western blotting in ARP1 and OPM2 myeloma cells." (PMID 28086949, 2017). "Both glucose uptake and lactate production decreased in NEK2 knockdown ARP1 and OPM2 myeloma cells compared to the control cells in both conditions." (PMID 28086949, 2017). "We then confirmed these gene expressions in NEK2 silenced ARP1 and OPM2 myeloma cells by real-time PCR." (PMID 28086949, 2017). "We conclude that NEK2 is a novel c-Myc target for regulation of PKM splicing and aerobic glycolysis in myeloma." (PMID 28086949, 2017). "Considering that NEK2 activates AKT and ABCB1 in myeloma, it is possible that ALDH1A1 promotes drug resistance by activating the NEK2-AKT pathway." (PMID 25230277, 2014). "Over expression of ALDH1A1 in myeloma cells led to increased mRNA and protein levels of NIMA-related kinase 2 (NEK2), whereas shRNA-mediated knock down of NEK2 decreased drug efflux pump activity and drug resistance." (PMID 25230277, 2014). "HNRNPA1/2 proteins may interact with NEK2 to regulate PKM splicing and promote aerobic glycolysis in multiple myeloma." (PMID 35897085, 2022). "It has been previously shown that (never in mitosis gene A)‐related kinase 2 (NEK2) is upregulated in multiple myeloma (MM) and contributes to drug resistance." (PMID 35088582, 2022). "It is not surprising because NEK2 was involved in malignant behavior in triple-negative breast cancer, lung cancer, hepatocellular cancer, and multiple myeloma, and indicated worse prognoses." (PMID 35705994, 2022). "FOXM1’s interaction with NIMA-related kinase 2 (NEK2) and the CDK4/6-Rb-E2F axis, in myeloma cells, is considered to be useful from a therapeutic aspect, because CDK inhibition is thought to be effective in myeloma treatment." (PMID 32679860, 2020). "The expression of PKM1 and PKM2 was measured by real-time PCR in myeloma cells with or without knockdown of NEK2." (PMID 28086949, 2017). "In this study, we have shown that NEK2 binds and interacts with hnRNPA1 and hnRNPA2, which control pyruvate kinase mRNA splicing in cancer cells, and increases PKM2 expression and PKM2/PKM1 ratio in myeloma cells." (PMID 28086949, 2017). "We have shown that overexpression of Nek2 promotes tumor cell growth and induces drug resistance in multiple myeloma and serves as a negative clinical prognostic indicator." (PMID 25485281, 2014). "Therefore, we hypothesize that NEK2 regulates alternative splicing of PKM2/PKM1 through interacting with hnRNPA proteins, leading to modulation of aerobic glycolysis in myeloma cells." (PMID 28086949, 2017).
multiple myeloma (continued). "However, treatment of myeloma cells with ATRA left NEK2 levels unchanged upon qPCR analysis (data not shown)." (PMID 25230277, 2014). "Following up on our previous work demonstrating that up-regulation of NEK2 leads to therapy resistance and inferior survival in patients with MM, we decided to explore whether NEK2 might be involved in the mechanism by which ALDH1A1 promotes drug resistance in myeloma." (PMID 25230277, 2014). "Although the molecular mechanism by which FOXM1 promotes drug resistance in myeloma has not yet been elucidated, FOXM1-dependent increases in cell proliferation, NEK2 (NIMA related kinase 2)-dependent CIN (chromosomal instability) and ABC-transporter drug-pump activity may be involved." (PMID 30463534, 2018).
hepatocellular carcinoma (28 papers, 2017 to 2026). A malignant tumor that arises from hepatocytes. "Improper expression and activity of NEK2 has been associated with the development of many cancers, such as lung cancer, hepatocellular carcinoma, multiple myeloma, and pancreatic cancer." (PMID 37046733, 2023). "The purpose of this study was to obtain NEK2 protein to prepare an anti-NEK2 monoclonal antibody (mAb) and explore the application of the anti-NEK2 mAb of therapeutic and diagnostic in hepatocellular carcinoma (HCC)." (PMID 34706700, 2021). "Negative regulations of NIMA-related kinase 2 (NEK2) in hepatocellular carcinoma and a repression of GRB2-associated-binding protein 2 (GAB2) in nonsmall cell lung cancer have been reported." (PMID 33298968, 2020). "In this regard, functional AQP3 and Nek2 is mutated or highly expressed in hepatocellular carcinoma, these molecular and cellular mechanisms may be overcome by the pharmacological action of AQP3/STAT3/CD133 pathway degradation and Nek2 inhibition." (PMID 35820920, 2022). "NEK2 was linked to inferior survival and poor prognoses in different cancers such as T-cell acute lymphoblastic leukemia, head and neck squamous cell carcinoma, bladder carcinoma, glioblastomas, hepatocellular carcinoma, and ovarian adenocarcinomas." (PMID 34072728, 2021). "NEK2 is upregulated in hepatocellular carcinoma (HCC) and is associated with adverse outcomes in patients with this disease." (PMID 38706902, 2024). "For example, NEK2 can reprogram glucose metabolism into aerobic glycolysis, and NEK2 induces sorafenib resistance in hepatocellular carcinoma tissue by binding to β-catenin." (PMID 40220284, 2025). "In hepatocellular carcinoma, NEK2 inhibits ubiquitination-proteasome degradation by binding β-catenin, thereby enhancing cell resistance to Sorafenib." (PMID 38503948, 2025). "Many malignancies, including cervical cancer, hepatocellular carcinoma, gastric cancer and lung cancer, have been reported to abnormally express NEK2." (PMID 38795132, 2024). "NEK2 is one of the better studied kinases in the NEK family and has been reported to be associated with disease progression for lung cancer, hepatocellular carcinoma, and pancreatic cancer." (PMID 37046733, 2023). "Another study identified miR-486-5p as an upstream regulator of NEK2 expression in hepatocellular carcinoma (HCC), thereby potentially opening a future therapeutic avenue to alleviate HCC progression." (PMID 35031599, 2022). "Increased expression of NEK2 through univariate and multivariate analyses revealed NEK2 as an independent indicator of a poor prognosis in hepatocellular carcinoma." (PMID 34072728, 2021). "Furthermore, Nek2 is the critical regulator of the centrosome, making hepatocellular carcinoma more resistance to current treatments." (PMID 35820920, 2022). "Several published studies have focused on the overexpression of NEK2 in hepatocellular carcinoma (HCC)." (PMID 32294979, 2020). "We analyzed the relationship between differential expression of NEK2 and hepatocellular carcinoma (HCC) patient outcomes after liver transplants." (PMID 28881785, 2017). "The same tumor, hepatocellular carcinoma, was promoted for recurrence also by the action of ECT2 and, along with NEK2 and DLGAP5, ECT2 was identified via a genome-scale analysis to act as a prognostic biomarker in lung cancer." (PMID 37106813, 2023). "Deregulation of NEK2(NIMA-related serine/threonine 2) confers chemotherapeutic resistance to apoptosis and is closely correlated with poor prognosis in hepatocellular carcinoma (HCC)." (PMID 36210464, 2022). "Moreover, the anti-NEK2 mAb was co-cultured with hepatocellular carcinoma (HCC) cells to investigate its effect on the proliferation of HCC cells and to provide a basis for NEK2-targeted drug research." (PMID 34706700, 2021).
hepatocellular carcinoma (continued). "In vitro studies have shown that NEK2 promotes cell proliferation by AKT and Wnt activation in NSCLC and hepatocellular carcinoma and via ERK/MAPK (extracellular signal-regulated kinase/mitogen-activated protein kinase) signaling in gastric cancer." (PMID 32504181, 2020). "Corroborating those studies, another group found high levels of NEK2 expression in human hepatocellular carcinoma HCC tissues and cell lines, which was correlated with clinical progression indicators such as tumor size, differentiation grade, and lymph node metastasis." (PMID 32294979, 2020). "Furthermore, this study demonstrates that TPGS-FA/NC suppresses hepatoma cell proliferation and hepatic CSCs, as well as the AQP3/STAT3/CD133 axis and Nek2 expression in offering possible multiple mechanisms for its antitumor activity." (PMID 35820920, 2022). "The upstream regulators of NEK2 are not clear and its prognostic role in hepatocellular carcinoma patients after liver transplantation is unclear." (PMID 28881785, 2017). "NEK2 has an established involvement in hepatocellular carcinoma (HCC) but the roles of NEK2 and its interacting proteins in HCC have not been systematically explored." (PMID 33109182, 2020). "NEK2 increases hepatocellular carcinoma (HCC) cell invasion by the epithelial–mesenchymal transition (EMT), and the various signaling pathways, including Wnt, NF-κB and focal adhesion which are predicted as downstream of NEK2 by gene expression microarray analysis." (PMID 39768163, 2024).
lung cancer (23 papers, 2015 to 2025). A malignant neoplasm involving the lung. "NEK2 was reported to be elevated in lung cancer, regulated by EGFR mutation." (PMID 35311097, 2022). "This included well-known lung-cancer-associated genes such as NEK2, suggesting that there may be a selective pressure for the deregulation of these lncRNAs in order to release these cancer-promoting genes from negative regulation." (PMID 33505435, 2020). "However, the association between the expression level of NEK2 and the early diagnosis of lung cancer patients remains to be rigorously and systematically evaluated." (PMID 28808310, 2017). "The present study identified and validated NUF2, KIF4A, KIF18B, DLGAP5, NEK2, and LRRK2 as promising diagnostic biomarkers for lung cancer." (PMID 36499051, 2022). "The overexpression of NEK2 in lung cancer patients compared with that in normal subjects has been reported, and the upregulation of NEK2 is related to poor overall survival, relapse-free survival, and increased risk of recurrence." (PMID 32294979, 2020). "Nek2 was reported as a prognostic biomarker for lung cancer, and knockdown of Nek2 gene with siRNA in xenograft mice decreased tumor size and increased survival for liver metastasized pancreatic cancer." (PMID 31379917, 2019). "Subsequently, ROC analysis was performed to assess the diagnostic value of NEK2, DLGAP5 and ECT2 as biomarkers detecting lung cancer." (PMID 28808310, 2017). "In lung cancer, high levels of NEK2 correlate with poor prognosis and aggressive disease." (PMID 40564876, 2025). "Additionally, NEK2 has also been found to be overexpressed and possess significant prognostic value in lung cancer." (PMID 36499051, 2022). "In addition, multiple data sets showed a significant increase in the expression of NEK2/4/6/8mRNA in lung cancer tissues." (PMID 35105934, 2022). "Furthermore, in order to assess the prognostic value of NEK2, DLGAP5 and ECT2 as biomarkers for lung cancer, we investigated the association between the expression levels of each of these targets with survival through Kaplan-Meier analysis." (PMID 28808310, 2017). "For the first time, we propose NUF2, KIF4A, KIF18B, DLGAP5, NEK2, and LRRK2 as biomarkers for lung cancer progression." (PMID 36499051, 2022). "It has been reported in previous literature that NEK2, TOP2A, PLK1, CA4, and AURKB can play oncogenic or tumor suppressing roles in the progression of lung cancer." (PMID 35646063, 2022). "The Cox proportional hazards regression model was also used to evaluate the predictive value of NEK2, DLGAP5 and ECT2 mRNA levels in lung cancer patients." (PMID 28808310, 2017). "The increased expression of NEK2, DLGAP5 and ECT2 in lung cancer was identified in three GEO datasets." (PMID 28808310, 2017). "The expression levels of NEK2, DLGAP5 and ECT2 were significantly higher in lung cancer patients than in normal subjects." (PMID 28808310, 2017). "In this study, we identified and validated the expression of NEK2, DLGAP5 and ECT2 in multiple lung cancer datasets, and the results showed that the expression levels of these three genes were significantly higher in lung cancer patients than in normal subjects." (PMID 28808310, 2017). "ROC analyses showed that NEK2, DLGAP5 and ECT2 levels could also robustly distinguish lung cancer patients from normal subjects, demonstrating high AUC, specificity and sensitivity values." (PMID 28808310, 2017). "Taken together, our findings revealed that NEK2, DLGAP5 and ECT2 might be used as promising biomarkers for the early detection of lung cancer, as well as predicting the prognosis of lung cancer patients." (PMID 28808310, 2017). "Collectively, our results suggest that NEK2, DLGAP5 and ECT2 could be suitable biomarkers for lung cancer diagnosis." (PMID 28808310, 2017). "Taken together, these findings indicate that NEK2, DLGAP5 and ECT2 overexpression might be used as promising biomarkers for the diagnosis and prognosis of lung cancer." (PMID 28808310, 2017).
lung cancer (continued). "In addition, compound 6 also inhibited the Nek2 (IC50: ~1.3 μM) kinase in A549 human lung cancer cell lines but lacked efficacy against the C22V Nek2 mutant." (PMID 35056661, 2022). "The expression levels of NEK2, DLGAP5 and ECT2 were similar to those in our training cohort, with significant differences in expression between tumor and normal, suggesting that the differential expression statuses of these three genes is a common feature of lung cancer." (PMID 28808310, 2017). "Furthermore, we performed receiver operating characteristics (ROC) analysis to assess the diagnostic value of these lung cancer biomarkers, and the results suggested that NEK2, DLGAP5 and ECT2 expression levels could robustly distinguish lung cancer patients from normal subjects." (PMID 28808310, 2017). "Results showed that there was overexpression of NEK2/4/6/8, low expression of NEK1/3/7, and no expression of NEK5/9/10/11 in lung cancer." (PMID 35105934, 2022).
colorectal cancer (20 papers, 2015 to 2025). A primary or metastatic malignant neoplasm that affects the colon or rectum. "Because NEK2 is known to be overexpressed in human colorectal cancer, we first evaluated the expression of NEK2 and RhoGDI1 in various human colon cancer cell lines." (PMID 39768163, 2024). "Increasing evidence has demonstrated that NEK2 is over-expressed in cervical cancer, breast cancer, head and neck squamous cell carcinoma, and colorectal cancer." (PMID 37233832, 2023). "Another study indicated that the patients with high expression of NEK2 showed greater tumor depth, lymphatic invasion and peritoneal dissemination in colorectal cancer." (PMID 35031599, 2022). "NEK2 is overexpressed in colorectal cancers compared to normal samples." (PMID 40076620, 2025). "Mechanistically, the overexpression of NEK2 in colorectal cancers may be regulated by upstream miRNA-128 methylation and FBXW7 circle RNA." (PMID 40076620, 2025). "Besides, a study conducted by Takahashi et al31 confirmed that expression of miR‐128 was negatively correlated with that of NEK2 expression in patients suffering from colorectal cancer." (PMID 32558224, 2020). "Circ-FBXW7 controls the progression of CRC through NEK2, mTOR, and PTEN signaling pathways and its overexpression inhibits colorectal cancer cell migration and invasion, suggesting the potential therapeutic target for CRC treatment." (PMID 31519156, 2019). "It has been reported that RPL17 could promote proliferation and stemness of colorectal cancer through ERK and NEK2/β-catenin signaling pathways." (PMID 36506302, 2022).